Y_RNA (Y RNA )
Gene: Miscellaneous RNA gene on chromosome 12 (95,275,770 to 95,275,872, forward strand). Ensembl gene ENSG00000202470.
Homologues: Orthologues: chimpanzee Y_RNA (100% identical), macaque Y_RNA (83% identical). Paralogues in human: Y_RNA (83% identical), RNY3 (82% identical), Y_RNA (82% identical), RNY3P12 (81% identical), Y_RNA (81% identical), Y_RNA (80% identical), RNY3P1 (79% identical), Y_RNA (79% identical), Y_RNA (78% identical), RNY3P2 (77% identical), RNY3P4 (77% identical), Y_RNA (77% identical), and 90 more.